SGO1 (shugoshin 1)
Diseases named in the same sentence as SGO1 in open-access papers (continued):
Sharing a sentence is not in itself a finding about the gene and the disease.
tumor (16 papers, 2012 to 2025). "In this study, we analyzed the SGO1 expression, prognostic value, diagnostic values, and correlation with tumor immune cell infiltration in LUAD for the first time." (PMID 35592680, 2022). "In addition, we employed the xCell method and found that the majority of the 38 immune cell subtypes were significantly associated with SGO1 expression across various tumor types." (PMID 40861810, 2025). "SGO1 expression was significantly associated with pathological stage (P = 0.001), T stage (P < 0.001), N stage (P = 0.005), M stage (P = 0.009), gender (P = 0.001), residual tumor gender (P = 0.019), and age (P = 0.006)." (PMID 35592680, 2022). "Then, GEPIA2 tool was used to summarize all tumor expression data of TCGA, and the top 10 genes related to SGO1 expression were obtained." (PMID 40861810, 2025). "In conclusion, by transcending the traditional view of SGO1 as a mitotic regulator, our work redefines it as a multifunctional orchestrator of tumor progression, immune evasion, and genomic instability." (PMID 40861810, 2025). "Taken together, these data suggest that SGO1 promotes tumor growth and metastasis both in vitro and in vivo." (PMID 40861810, 2025). "We utilized the Human Protein Atlas (HPA) database to further investigate the expression differences of SGO1 between tumor and normal tissues by immunohistochemistry." (PMID 40861810, 2025). "To summarize, these results suggest an important role for SGO1 in tumor growth and metastasis in TNBC." (PMID 37122033, 2023). "Our results showed that SGO1 downregulation significantly reduced tumor growth and metastasis of TNBC to the lungs and lymph nodes." (PMID 37122033, 2023). "Haplo-insufficiency of either BubR1 or SGO1 results in enhanced chromosomal instability and tumor development in the intestine." (PMID 26847209, 2016). "Using the TIMER method, we found that SGO1 is significantly associated with the infiltration levels of various immune cells, including B cells, CD8+ T cells, CD4+ T cells, macrophages, neutrophils, and dendritic cells across different tumor types." (PMID 40861810, 2025). "Additionally, employing the xCell method, we discovered that the expression of SGO1 is significantly correlated with most of the 38 immune cell subtypes in different tumor types, especially Th2 cells." (PMID 40861810, 2025). "The correlation between SGO1 expression and tumor cells behavior evident in both MDA-MB-231 and A549 models, combined with in vivo validation through xenografting, underscored SGO1's potential as a key player in tumorigenesis and a promising target for therapeutic intervention." (PMID 40861810, 2025). "We analyzed the Spearman correlation between SGO1 expression and DNAss in each tumor." (PMID 40861810, 2025). "Furthermore, the tumor xenograft experiments demonstrated that the tumorigenic potential of the SGO1-silenced group was lower than that of the control mice." (PMID 40861810, 2025). "We also observed that SGO1 expression affected tumor purity in 16 tumor types." (PMID 40861810, 2025). "Given its role in cell division and the marked effect on tumor growth, we hypothesized that the downregulation of SGO1 will affect cell viability." (PMID 37122033, 2023). "Therefore, we aimed to investigate the effects of sustained shRNA-mediated SGO1 downregulation on tumor growth and metastasis in TBNC." (PMID 37122033, 2023). "Another explanation is that SGO1 may reduce tumor growth (and thus metastasis) due to its role in cell division." (PMID 37122033, 2023). "MiR-125a-5p was selected as the most potential upstream tumor-suppressive miRNA of SGO1." (PMID 35592680, 2022).
tumor (continued). "As expected, Sgo1 mRNA levels in precancerous and tumor samples were high." (PMID 27539729, 2016). "However, the specific roles of SGO1 in different tumor types and its potential mechanisms remain unclear." (PMID 40861810, 2025). "However, this is the first study that shows a role for SGO1 in tumor growth and metastasis in TNBC." (PMID 37122033, 2023). "Therefore, the stable silencing of SGO1 greatly reduces tumor growth, while suppressing metastasis." (PMID 37122033, 2023). "However, it is unknown if the stable downregulation of SGO1 would suppress tumor growth and metastasis of TNBC." (PMID 37122033, 2023). "Our results suggest that the suppression of tumor growth and metastasis in TNBC following SGO1 downregulation are in part mediated by Snail and Slug." (PMID 37122033, 2023). "Shugoshin 1 (SGOL1) plays a crucial role in cell mitosis and its aberrant expression level in human tumors has shown to promote chromosomal instability (CIN) and accelerate tumor growth." (PMID 36439418, 2022).
infection (1 paper, 2023). The state of being infected such as from the introduction of a foreign agent such as serum, vaccine, antigenic substance or organism. "On the other hand, cohesion of sister chromatids is a dynamic process regulated by genes such as Cdca5, Cdca8(Borealin), Plk1, Sgo1, and Sgo2a, which were up-regulated late in infection." (PMID 38107402, 2023).
SGO1 also shares sentences with these, for which no sentence is quoted: Cornelia de Lange syndrome (5 papers); cardiac dysrhythmia (2); diffuse large B-cell lymphoma (2); glioblastoma (2); neuropathy (2); Roberts-SC phocomelia syndrome (2); skin cutaneous melanoma (2); Warsaw breakage syndrome (2); acute myeloid leukemia (1); adenocarcinoma (1); Alpha-thalassemia (1); Bradycardia (1); CHOPS syndrome (1); chronic intestinal pseudo-obstruction (1); chronic lymphocytic leukemia (1); clear cell renal cell carcinoma (1); colon adenocarcinoma (1); cytomegalovirus infection (1); hematological cancers (1); hematological malignancies (1); kidney (1); lymphoid neoplasm (1); lymphoproliferative disorders (1); mild cognitive impairment (1); mitochondrial disease (1); myopathy (1); osteosarcoma (1); pancreatic adenocarcinoma (1); pancreatic ductal adenocarcinoma (1); rectum adenocarcinoma (1).
A further 8 diseases each share a sentence with SGO1 in 1 paper.